OR51F2 (olfactory receptor family 51 subfamily F member 2)
Description:
Odorant receptor.
Synonyms: OR11-23
Tractability: Antibody: UniProt places it where antibodies can reach, with medium confidence; UniProt predicts a signal peptide or a membrane-spanning region; its Gene Ontology location is reachable by antibodies, with medium confidence.
Gene: Protein-coding gene on chromosome 11 (4,821,321 to 4,822,456, forward strand). Ensembl gene ENSG00000176925.
Subcellular location: Cell membrane
Pathways (Reactome):
Sensory Perception: Expression and translocation of olfactory receptors
Gene Ontology:
Molecular function: olfactory receptor activity; G protein-coupled receptor activity; signaling receptor activity
Biological process: cellular response to lipid; detection of chemical stimulus involved in sensory perception of smell; G protein-coupled receptor signaling pathway; system process
Cellular component: plasma membrane; membrane
Genetic constraint (gnomAD): Loss-of-function variants: 0 observed, 0.6 expected, observed/expected ratio (o/e) 0, 90% interval 0 to 1.82. That is too few expected variants to judge how well the gene tolerates losing a copy. Missense variants: 435 observed, 409.57 expected, observed/expected ratio (o/e) 1.06, 90% interval 0.98 to 1.15. Synonymous variants: 172 observed, 155.12 expected, observed/expected ratio (o/e) 1.11, 90% interval 0.98 to 1.26.
Homologues: Orthologues: chimpanzee OR51F2 (98% identical), rabbit OR51F2 (82% identical), rat Or51f2 (82% identical), mouse Or51f2 (79% identical), pig OR51F2 (79% identical). Paralogues in human: OR51C1 (55% identical), OR51G2 (52% identical), OR51L1 (51% identical), OR51I2 (50% identical), OR51T1 (48% identical), OR51G1 (47% identical), OR51I1 (47% identical), OR51A7 (47% identical), OR52N5 (47% identical), OR51A4 (46% identical), OR52N4 (46% identical), OR51M1 (45% identical), and 39 more.
Diseases named in the same sentence as OR51F2 in open-access papers:
OR51F2 is named in the same sentence as 1 disease in open-access papers, as found by Europe PMC text mining. Sharing a sentence is not in itself a finding about the gene and the disease.
OR51F2 shares sentences with these, for which no sentence is quoted: pancreatic cancer (3 papers).